TERT (telomerase reverse transcriptase)
Diseases named in the same sentence as TERT in open-access papers (continued):
Sharing a sentence is not in itself a finding about the gene and the disease.
metastatic disease (41 papers, 2014 to 2026). "On multivariate analysis, age (more than 45 years), presence of metastatic disease and tumors harboring telomerase reverse transcriptase (TERT) promoter mutations were independent prognostic factors for poor DTC-specific survival." (PMID 38812819, 2024). "We also the hotspot detected the promoter TERT C228T mutation in both the patient's metastatic tumor and HCB-541 cell line by NGS panel and further confirmed by droplet digital PCR (ddPCR)." (PMID 38565739, 2024). "This supposition is further supported by the finding that the majority of CM with metastatic disease revealed either ATRX loss or a TERT promoter mutation." (PMID 37629169, 2023). "Fifteen patients with conjunctival melanoma developed recurrent disease and eleven patients with conjunctival melanoma developed metastatic disease, with most of the cases with metastatic disease harboring either a TERT promoter mutation or ATRX loss." (PMID 37629169, 2023). "Since most CMs with metastatic disease show either ATRX loss or a TERT promoter mutation, both alterations are suggestive of an association with adverse clinical behavior." (PMID 37629169, 2023). "About three quarter of CM contain drug-targetable mutations, and TERT promoter mutations are correlated to metastatic disease in CM." (PMID 34071371, 2021). "Within this study, we confirmed that TERT promoter mutations are frequently found in CM and are correlated to metastatic disease, supporting the relevance of molecular genetic testing for prognostic reasons." (PMID 34071371, 2021). "It is worth noting that the presence of a TERT promoter mutation was able to influence the prognosis even in our group 3, with metastatic disease." (PMID 33790328, 2021). "The presence of TERT-p mutations was significantly associated with the risk of extranodal metastatic disease or death (P < 0.0001)." (PMID 26061100, 2015). "In total, 2/9 of patients with ccRCC carrying TERT promoter mutations had metastatic disease while the corresponding fraction among patients with mutation-negative tumors was only 4/87." (PMID 24742867, 2014). "Although we confirmed TERT/ATRX-alterations are associated with metastatic disease, the utility of these mutations as predictive biomarkers may be limited by the late timing of these events." (PMID 38978571, 2024). "Finally, the distribution of TERT promoter mutations was compared between primary and metastatic tumor samples." (PMID 37462445, 2024). "Metastatic disease is linked to TERT promoter mutations in conjunctival melanomas (CM)." (PMID 37629169, 2023). "Furthermore, shorter disease-specific survival was observed in those with wild-type primary tumors who later developed TERT-mutated metastasis compared with those with metastatic disease who remained wild type." (PMID 34108637, 2021). "Presence of a TERT promoter mutation was associated with metastatic disease (p-value = 0.008)." (PMID 34071371, 2021). "We found a higher prevalence of TERT promoter mutations in patients with metastatic disease." (PMID 33790328, 2021). "The presence of TERT promoter mutations predicts metastatic disease in UTUCs." (PMID 25474136, 2014). "In addition, TERT alterations may be associated with adverse outcomes such as metastatic disease and death from disease." (PMID 34549366, 2022). "Somatic variants in the TERT promoter were associated with aggressive tumor features, such as extra-adrenal location, germline SDHB PVs, and metastatic disease." (PMID 42155081, 2026). "In acral lentiginous melanoma, TERT amplification was observed to be involved in the progression to metastatic disease." (PMID 40361989, 2025). "CDKN2A and CKDN2B deletions and BRAF and TERT amplifications were common in the metastatic tumors of SUM and AM." (PMID 37686691, 2023).
metastatic disease (continued). "They found nine patients with different BRAF, NRAS, or TERT genotypic profiles between their metastatic tumors." (PMID 35887633, 2022). "All 3 patients had amplifications of the TERT gene and had metastatic disease at diagnosis or on follow up, and at least 2 patients were dead of cancer-related causes at last follow up." (PMID 34549366, 2022). "Patients with HRNB frequently present with widely metastatic disease, with tumors harboring recurrent genetic aberrations (MYCN amplification, TERT rearrangements, and ATRX mutations), which are mutually exclusive and capable of promoting TMM." (PMID 34439779, 2021). "Viral integration in the TERT gene occurred early in the history of tumour progression and was also found in all tumour samples for patients 1 and 8 (including the metastatic tumour for patient 1)." (PMID 28240289, 2017). "All three patients with metastatic disease had a TERT promoter wild-type tumor." (PMID 39363120, 2024). "TERT promoter mutations were also enriched in Class 2 but not in Class 3 BRAF mutant metastatic tumors." (PMID 38275886, 2024). "The TERT rs2853669 CC+TC genotypes (38%) were overrepresented in metastatic tumors." (PMID 37569841, 2023). "In conclusion, in the hitherto largest study of TERT promoter mutations in conventional CS, we observed that TERT promoter mutation was a negative prognostic marker, with a clear, significant correlation to high tumor grade, metastatic disease, and mortality." (PMID 34108637, 2021). "Interestingly, we demonstrated that the presence of a strong pre-existing anti-TERT Th1 response in blood was significantly associated with better OS in NSCLC patients with both localised and metastatic disease." (PMID 31358938, 2019). "The highest frequency variant in all samples was mutation of the promoter region of TERT with an identified frequency of 70% in progressors, 66% in non-progressors (p = 0.99), and 82% among patients with metastatic disease." (PMID 27750214, 2016). "Altogether, distant metastatic disease occurred in eight of 64 (12.5%) and 2 of 155 (1.3%) patients with tumors carrying and lacking TERT promoter mutations, respectively (P = 0.001, X 2 test)." (PMID 25474136, 2014). "Only one CM case with metastatic disease revealed neither a TERT promoter mutation nor ATRX loss." (PMID 37629169, 2023). "Two cases with metastatic disease without a TERT promoter mutation did show ATRX loss." (PMID 37629169, 2023). "A TERT promoter mutation was found in eight of eleven cases with metastatic disease, with no ATRX loss in six cases and unknown ATRX status in two cases." (PMID 37629169, 2023). "In both RPCs and UCs, however, distant metastasis was closely associated with the presence of TERT promoter mutations: All 4 RPC patients with distant metastasis were mutation-positive whereas none of 56 patients with a wild-type TERT promoter had metastatic disease (P = 0.013, Fisher exact test)." (PMID 25474136, 2014). "A significant difference was identified between the ratios of cytoplasmic TERT/nuclear TERT in non-metastatic xenograft tumor tissues, metastatic tumor tissues and metastatic lymph nodes." (PMID 25435972, 2015). "In conclusion, as HPV status, integration status, TERT promoter mutations, and mutational profiling are not significantly correlated to PFS and/or OS in this study, DCF chemotherapy should be proposed to all SCCA patients failing radio-chemotherapy (CRT) or with metastatic disease." (PMID 36313663, 2022).
metastatic disease (continued). "Ten primary tumours from patients with metastatic disease did not have TERT/ATRX-alterations, but the late acquisition of TERT/ATRX alterations and presence in metastatic cells could not be excluded given that the metastatic tissue was not sequenced." (PMID 38978571, 2024).
pancreatic cancer (36 papers, 2010 to 2026). "The two pancreatic cancer cell lines express higher levels of TERT from the C as compared to the G allele (2.3 and 9.8 fold, respectively) whereas A549 cells express higher levels from the G allele." (PMID 28447668, 2017). "Furthermore, evidence has demonstrated that the TERT hypermethylated oncologic region predicts recurrence and survival in pancreatic cancer is associated with higher TERT expression and higher-risk disease in non-muscle-invasive bladder cancers (NMIBC)." (PMID 39000438, 2024). "However, some studies have found that mutations in the TERT promoter are rare in pancreatic cancer cases." (PMID 38594465, 2024). "UBE3A interacts with mH2A1 through its N-terminal domain, leading to K48-linked polyubiquitination at the K167 residue, which accelerates mH2A1 degradation and upregulates TERT, enhancing the anti-senescence capacity of pancreatic cancer cells." (PMID 41748542, 2026). "In immunotherapy, one of the TERT vaccines currently in clinical research for pancreatic cancer is called GV1001." (PMID 38594465, 2024). "Specifically, in PDAC, TGF-β can induce telomerase-dependent pancreatic tumor cell cycle arrest by stimulation of the G1/S transition via TERT over-expression." (PMID 36843111, 2023). "The results showed that the interaction of TERT and TERC decreased after knockdown of LDHB, which suggested that LDHB regulates telomerase activity in pancreatic cancer cells by affecting the assembly of TERT and TERC." (PMID 35669414, 2022). "Detailed mechanistic insights provided new information about binding of Mxd1 to the promoter region of TERT which substantially reduced c-Myc binding to TERT promoter in pancreatic cancer cells." (PMID 29614790, 2018). "Common low penetrance variants in gene loci including ABO, TERT and PDX1 that contribute to pancreatic cancer risk have been identified through genome-wide association studies, but much of the familial clustering of pancreatic cancer remains unexplained." (PMID 28881607, 2017). "Single nucleotide polymorphisms (SNPs) in ABO, sonic hedgehog (SHH), telomerase reverse transcriptase (TERT), nuclear receptor subfamily 5, group A, member 2 (NR5A2) were found to be associated with pancreatic cancer risk." (PMID 22125638, 2011). "Several single nucleotide polymorphisms (SNPs) in the gene regions of ABO, sonic hedgehog (SHH), telomerase reverse transcriptase (TERT), nuclear receptor subfamily 5, group A, member 2 (NR5A2) were found to be associated with pancreatic cancer risk." (PMID 22125638, 2011). "The UBE3A/mH2A1/TERT axis enhances the anti-senescence capacity of pancreatic cancer cells and drives malignant progression, suggesting that UBE3A may serve as a novel therapeutic target for pancreatic cancer." (PMID 41748542, 2026). "In vitro experiments show that BIBR1532 can not only cause DNA damage to pancreas cancer samples and promote cancer stem cells(CSC) apoptosis, but also reduce the expression of TERT, prevent the number of CSCs in organoid culture medium and thus prevent them from forming spheres." (PMID 38594465, 2024). "At chr5p15.33, one of the four variants highly correlated with rs35226131 is a missense variant in the second exon of TERT (rs61748181: r2 = 1, D' = 1 in 1000G EUR) whereby the minor allele, associated with reduced risk of pancreatic cancer, changes amino acid 279 from alanine to threonine (A279T)." (PMID 27579533, 2016). "Therefore, at present, the development of pancreatic cancer may be due to a different mechanism, namely methylation of the TERT promoter." (PMID 38594465, 2024). "The third endometrial cancer risk SNP identified in this study is in the upstream/promoter region of CLPTM1L, ~60 kb away from TERT, and which also harbours several cancer risk alleles, mostly for non-hormone-related malignancies such as lung, bladder and pancreatic cancers." (PMID 25487306, 2015).
pancreatic cancer (continued). "Methylation of the telomerase reverse transcriptase (TERT) promoter and regulation of telomerase by lactate dehydrogenase B (LDHB) is the mechanism of telomerase reactivation in pancreatic cancer." (PMID 38594465, 2024). "Differential ZNF148 binding to the rs36115365 SNP was particularly intriguing because it is located 18 kb upstream of the 5′-end of TERT, and ZNF148 mRNA knockdown in a panel of pancreatic cancer cell lines resulted in reduced TERT expression." (PMID 37918959, 2023). "In this study, we investigated the potential relation with metabolic enzymes and telomerase activity in pancreatic cancer and identified that LDHB interacted with TERT and regulated telomerase activity independent of its metabolism regulating function." (PMID 35669414, 2022).
lymph node metastasis (33 papers, 2011 to 2025). "Tumors harboring BRAF+TERT co-mutations demonstrated particularly aggressive features, with 60% lymph node metastasis (6/10 cases) and a mean tumor diameter of 16.8 mm." (PMID 40805132, 2025). "The presence of both the BRAF V600E and TERT mutations is synergistic and substantially increases the risk of lymph node metastasis, recurrence, and disease-specific mortality rates." (PMID 37623013, 2023). "TERT promoter mutations in lymph node metastases were significantly associated with lower iodine avidity, with a 10-fold lower avidity (CI 1.7–60)." (PMID 37352166, 2023). "Mutations in BRAF and the TERT promoter were significantly associated with lower iodine avidity for lymph node metastases (18-fold and 10-fold, respectively)." (PMID 37352166, 2023). "Patients with TERT promoter mutated cSCC were found to be at higher risk of local recurrence and lymph node metastases." (PMID 36980718, 2023). "TERT C228T alone was significantly associated with lymph node metastasis, and there was an insignificant association with other clinicopathological characteristics." (PMID 36704521, 2022). "Based on various reports, BRAF and TERT mutation are associated with the older age, female gender, bigger tumor size, extrathyroidal extension, lymph node metastasis, multifocality, advanced stage, and recurrence." (PMID 33247684, 2020). "Meta-analysis showed significant association of BRAF V600E+/TERT+ co-mutations with lymph node metastasis, multifocality, distant metastasis, tumor recurrence, extrathyroidal extension, and dead of disease." (PMID 31300059, 2019). "Coexistence of BRAF V600E and TERT promoter mutations were significantly correlated with lymph node metastasis, multifocality, distant metastasis, tumor recurrence, extrathyroidal extension, and dead of disease." (PMID 31300059, 2019). "Presently, our meta-analysis provided strong evidence that BRAF V600E/TERT promoter mutations were significantly correlated with lymph node metastasis, multifocality, distant metastasis, tumor recurrence, extrathyroidal extension, and dead of disease." (PMID 31300059, 2019). "Statistically meaningful association is found between TERT promoter mutations and older age, larger tumor size, extrathyroidal extension, lymph node metastasis, distance metastasis, advanced TNM stage, recurrence, and BRAF V600E mutation." (PMID 30024548, 2018). "These cases often exhibited adverse clinicopathological features such as capsular invasion, lymphatic invasion, angioinvasion, minimal ETE, infiltrative and invasive capsule status, high AJCC pT stage, BRAF V600E mutations, TERT promoter mutations, lymph node metastasis, and synchronous metastasis." (PMID 40312532, 2025). "Meta-analyses have shown that patients with a BRAF V600E mutation, especially in combination with a TERT promoter mutation, have a higher risk of unfavorable clinicopathological parameters such as extrathyroidal tumor spread, lymph node metastasis, and a higher TNM stage." (PMID 38616265, 2024). "We included all nine studies in the meta-analysis (heterogeneity: Chi2 = 8.58, I2 = 18%, Z = 3.55, P < .01, fixed efforts model), finding that TERT promoter mutations can increase the risk of lymph node metastasis with the odds ratio (OR), 1.85; 95% CI; [1.32–2.59] P = .0004." (PMID 30024548, 2018). "PTCs with TERT+BRAF mutation had lateral lymph node metastasis more frequently than PTCs with BRAF mutation alone (OR = 22.557, 95% CI = 2.181–233.294) and demonstrated non-parallel orientation on US more frequently than PTCs without any mutation (OR = 11.282, 95% CI = 1.008–126.270)." (PMID 29312581, 2017). "The hazard ratio (HR) for tumor recurrence in patients with BRAFV600E and TERT promoter mutations was 6.74 (95% CI: 2.17–20.91, p = 0.001) (upper), which remained significant after adjustment for patient age, sex, and lymph node metastasis (HR: 4.17, 95% CI: 1.06–17.7, p = 0.048) (upper)." (PMID 28150740, 2017).